RPGR (retinitis pigmentosa GTPase regulator)
Diseases named in the same sentence as RPGR in open-access papers (continued):
Sharing a sentence is not in itself a finding about the gene and the disease.
Retinal dystrophy (31 papers, 2012 to 2026). Retinal dystrophy is an abnormality of the retina associated with a hereditary process. "Mutations of TTLL5 cause retinal dystrophy in humans, presumably because of impaired glutamylation of the X-linked Retinitis Pigmentosa GTPase regulator RPGR." (PMID 39528655, 2024). "In the group with only ocular involvement, we observed 6 cases of (probably) pathogenic variants in genes associated with retinal dystrophies (RPGR; N = 2, CACNA1F; N = 2, RP2, NDP), which corresponds to 27.3% of all genetically confirmed cases of HM." (PMID 39495751, 2024). "RPGR mutations are also associated with other retinal dystrophies, such as cone-rod dystrophy and atrophic macular degeneration, indicating that RPGR is crucial for the maintenance of retinal stability." (PMID 37351277, 2023). "Although female carriers of RPGR mutations generally present with mild phenotypes, severe retinal dystrophy has been reported in approximately 23% of carriers." (PMID 36607619, 2023). "Within the spectrum of RP-related retinal dystrophy, several gene therapy studies have been published for the replacement of specific mutated genes, such as RPGR MERTK, RLBP1 and PDE6B." (PMID 37762059, 2023). "Previous studies have indicated that RPGR variants are also responsible for other XL inherited retinal dystrophies (IRDs), including cone dystrophy 3(COD3, OMIM #602093), cone-rod dystrophy 2 (CORD2, OMIM #120970), and macular degeneration." (PMID 36276946, 2022). "Our previous study reveals that RPGR mutations, with a prevalence of 4% in the Chinese population, were ranked as the fourth most common genetic mutation in patients with inherited retinal dystrophy (IRD)." (PMID 35432464, 2022). "Mutations in the Retinitis Pigmentosa GTPase Regulator (RPGR) cause retinal dystrophy, but how this arises at a molecular level is unclear." (PMID 28814713, 2017). "Most importantly, MT glutamylation is not affected in the retina of MmTTLL5 KO mice, indicating that the retinal dystrophy phenotype is specifically due to the loss of RPGR glutamylation." (PMID 29176602, 2017). "Indeed, within our study cohort, approximately 15% of all individuals with RPGR-associated retinal dystrophy were carrier females manifesting a disease phenotype." (PMID 38219857, 2024). "Furthermore, a specific isoform of RPGR is a substrate for TTLL5 and mutations in TTLL5 cause retinal dystrophy in humans and slow photoreceptor degeneration in mice leading to the proposal that glutamylation of RPGR is required for its normal function." (PMID 35404950, 2022). "RPGR is a well-known retinal dystrophy disease-causing gene, but VUSs may be identified in this gene, which hamper clinical management decisions and access to clinical trials." (PMID 35330501, 2022). "Interestingly, in mice, the RPGRORF15 (the photoreceptor-specific ORF15 variant of retinitis pigmentosa GTPase regulator) implicated in retinal dystrophy actually localizes to connecting cilia of photoreceptors and is glutamylated by TTLL5 in vivo." (PMID 33748109, 2021). "Our study demonstrates the highly variable phenotype found in RPGR-associated retinal dystrophies." (PMID 32012938, 2020). "High myopia is a feature of several inherited retinal diseases, including retinitis pigmentosa GTPase regulator (RPGR)-related retinal dystrophy which has among the highest level of myopic refractive error." (PMID 40535564, 2025). "Specifically, HM was identified in six children with retinal dystrophies (RPGR; N = 2, CACNA1F; N = 2, RP2, NDP) and one child each of corneal dystrophy (ZEB1) and Stickler syndrome (causative variant in the COL9A2 gene)." (PMID 39495751, 2024). "Disrupted transcriptional regulation of RPGR, which is finely tuned in photoreceptors, likely contributes to the retinal dystrophy phenotype." (PMID 38699732, 2024).
Retinal dystrophy (continued). "Among cases of high myopia with ocular involvement (38.9%), a genetic cause was found in 8 out of 14 probands, including (likely) pathogenic variants in genes related to retinal dystrophies (CACNA1F, RPGR, RP2, NDP)." (PMID 39495751, 2024). "She worked on mutations in retinitis pigmentosa GTPase-regulator (RPGR) gene that cause X-linked retinitis pigmentosa, a subtype of retinal dystrophy." (PMID 36239357, 2022). "To explore the RPGR genotype–phenotype relationship, we studied 116 patients with RPGR retinal dystrophy—the largest reported RPGR patient cohort to date." (PMID 36445968, 2022). "Leber congenital amaurosis (LCA) caused by RPGR or RP2 mutation, which is one of the most severe forms of inherited retinal dystrophy, was reported in a Chinese cohort." (PMID 30917587, 2019). "Mutations in the Retinitis Pigmentosa GTPase Regulator (RPGR) cause X-linked RP (XLRP), an untreatable, inherited retinal dystrophy that leads to premature blindness." (PMID 28814713, 2017). "Mutations in the gene encoding retinitis pigmentosa GTPase regulator (RPGR) are the most common cause of X-linked retinitis pigmentosa (XLRP) and are estimated to cause 20% of all retinal dystrophy cases." (PMID 22563472, 2012). "Our findings suggest that G4 formation in the RPGR gene could lead to genetic instability and affect the expression of RPGR, contributing to retinal dystrophy." (PMID 38699732, 2024). "Moreover, gene therapy for RPGR-related retinal dystrophies is currently being tested in multiple studies, and the identification of patients who may benefit from this therapy is important." (PMID 35432464, 2022). "Thirty (60%) had RPGR-related retinal dystrophy, nine (18%) had ABCA4-Stargardt disease, five (10%) had KCNV2-related retinal dystrophy, three (6%) had RDH12-related retinal dystrophy, two (4%) had Achromatopsia, and one (2%) had Usher syndrome." (PMID 39641965, 2024). "Following that the loss of the TTLL5 enzyme leads to a cone-dominated phenotype, where full-length RPGR would not be glutamylated, we hypothesize that the phenotype of the distal pathogenic RPGR variants would merge with the TTLL5 retinal dystrophy." (PMID 36445968, 2022).
Cone rod dystrophy (24 papers, 2008 to 2025). "Mutations in RPGR have also been associated with cone-rod dystrophy (CORD) and X-linked atrophic macular degeneration." (PMID 33748110, 2021). "Regarding RPGR, 3% of mutations in this ciliary gene have been associated with X-linked atrophic macular degeneration (MIM 300834)." (PMID 33748110, 2021). "RPGR interacts with several other ciliary proteins, some of which have also been associated with cone/cone-rod dystrophy (reviewed in Discussion)." (PMID 33805381, 2021). "Mutations in RPGR are associated with X-linked RP, as well as with X-linked cone dystrophy, cone-rod dystrophy, and an atrophic form of macular degeneration." (PMID 27995965, 2016). "RPGR mutations are often associated with rod-cone degeneration that is highly variable in degree of severity." (PMID 22563472, 2012). "In some instances, RPGR mutations are associated with cone-rod degeneration, atrophic macular degeneration, and syndromic phenotypes." (PMID 22563472, 2012). "RPGR is the causative gene in approximately 1% cases of cone/cone-rod dystrophy." (PMID 33805381, 2021). "Some insight into the pathogenesis behind RPGR-cone/cone-rod dystrophy may be gained by studying the proteins that interact with RPGR and also associate with the phenotype above." (PMID 33805381, 2021). "In addition, certain RPGR mutations are involved in cone-rod dystrophy (CRD)." (PMID 27493202, 2016). "Variation in phenotypes in RPGR contributes to multiple disease patterns, including rod-cone dystrophy (70%), cone-rod dystrophy (6–23%), and cone dystrophy (7%)." (PMID 39941570, 2025). "Loss-of-function of RPGR generally causes X-linked retinitis pigmentosa (XLRP); however, certain variants are more frequently associated with cone or cone-rod dystrophy." (PMID 41153400, 2025). "Pathogenic variants of RPGR cause a range of phenotypes, including rod-cone dystrophy (RCD, also known as RPGR-associated RP), early-onset severe retinal dystrophy (EOSRD), cone-rod dystrophy CORD, cone dystrophy (COD), macular atrophy, and syndromic XLRP." (PMID 39199291, 2024). "The other IRD group included Stargardt's disease carrying ABCA4 variants, as well as individuals with Cone-Rod Dystrophy (CORD) or RP presenting with various genetic variants such as RDH12, RPGR, LCA5,CEP290, RP2, USH2A, and EYS." (PMID 38466290, 2024). "Variants in RPGR are associated with X-linked IRD with a range of phenotypes including RP (most common), cone-rod dystrophy, and isolated cone dystrophy." (PMID 38219857, 2024). "RPGR mutations in the shared sequence of RPGR isoforms are known to cause retinal disease phenotypes, including RCD, cone-rod dystrophy and cone dystrophy, with a predominance of the RCD phenotype in the exon 1-14 region." (PMID 35330501, 2022). "RPGR was included as part of this screening as ORF15 variants can result in cone-rod dystrophy, but it is not captured as efficiently as other targets." (PMID 36672932, 2023). "Variants in the X-linked retinitis pigmentosa GTPase regulator gene (RPGR) and, specifically, in its retinal opening reading frame-15 isoform (RPGRORF15) may cause rod-cone (RCD), cone, and cone-rod dystrophies (CDs and CRDs)." (PMID 35806195, 2022). "Recently, cone/cone-rod dystrophy was also described in patients harbouring mutations in TTLL5 (tubulin tyrosine ligase like-5) and ARL3 (Arf-like protein 3), both interacting partners of RPGR." (PMID 33805381, 2021). "Interestingly, an affected male cousin of patient P3 had a symmetrical, nonsectorial phenotype of cone-rod dystrophy, despite harboring the same RPGR variant." (PMID 32795431, 2021). "Interestingly, 3’-terminal mutations in RPGR exon ORF15 are occasionally associated with cone-rod degenerations rather than classic RP." (PMID 18552978, 2008).
retinal disease (19 papers, 2007 to 2025). "Female carriers of X-linked RP associated with RPGR variants (referred to as RPGR carriers hereafter) exhibit variable retinal disease severity, ranging from subretinal normal retinae to severe degeneration; the latter is known as the “male pattern” phenotype." (PMID 40004550, 2025). "X-linked retinitis pigmentosa (XLRP) is a severely blinding retinal disease, most of which are due to mutations in retinitis pigmentosa GTPase regulator (RPGR)." (PMID 41288322, 2025). "This study provides new insights into the mechanisms underlying RPGR-associated retinal diseases and offers potential therapeutic approaches." (PMID 41288322, 2025). "In conclusion, our data support that the RPGR pathogenic variant likely is a functionally null mutation that causes defects in ciliary properties associated with retinal diseases as observed in the family described herein." (PMID 37541846, 2023). "Among the 277 described RPGR ORF15 inherited retinal disease variants (data from the HGMDPro database), only 47 were associated with COD and CORD." (PMID 37895299, 2023). "This process is highly regulated and involves several proteins associated with retinal disease, including RPGR, RPGRIP1, and CEP290." (PMID 34257417, 2022). "Mutations in RPGR were the causative genetic defect in seven female carriers who presented milder or comparable retinal disease to that encountered in the affected males of the pedigree." (PMID 36460718, 2022). "Retinitis pigmentosa GTPase regulator (RPGR)-related retinal disease is the commonest form of X-linked and recessive retinitis pigmentosa (RP) accounting for approximately 20% of all RP cases." (PMID 36445968, 2022). "Candidate modifier loci were chosen on the basis of previously demonstrated protein-protein interaction with RPGR, known retinal disease-causing mutations, and known common protein variation." (PMID 21857984, 2011). "A candidate modifier-gene approach was taken to screen genes meeting the following criteria: 1) the protein is known to interact with RPGR, 2) the protein has polymorphic amino acid substitutions, and 3) the gene contains known retinal disease-causing mutations." (PMID 21857984, 2011). "This cross-sectional study was based in two Australian sites (Melbourne and Perth) and assessed a comparatively large cohort of RPGR carriers and healthy controls to describe the retinal disease spectrum using retinal imaging and microperimetry." (PMID 40004550, 2025). "As such, it is crucial to identify sensitive retinal biomarkers for detecting and monitoring retinal disease and accurately assess the suitability of RPGR carriers for upcoming therapeutic interventions." (PMID 40004550, 2025). "In the current study, LLVA was found to diminish with an increasing retinal disease severity in RPGR carriers, making it a valuable biomarker for distinguishing between different retinal phenotypes of RPGR carriers." (PMID 40004550, 2025). "In the current study, RPGR carriers exhibited almost perfect agreement in terms of retinal disease severity between eyes, a phenomenon consistent with prior research findings." (PMID 40004550, 2025). "While early successes like LUXTURNA have set the precedent for gene therapy in retinal diseases, adapting these strategies to XLRP presents unique challenges due to the complexity of RPGR mutations and the need for efficient photoreceptor targeting." (PMID 39941570, 2025). "Variants within the Retinitis Pigmentosa GTPase regulator (RPGR) gene are the predominant cause of X-Linked Retinitis Pigmentosa (XLRP), a common and severe form of inherited retinal disease." (PMID 38339118, 2024). "A subset of patients was screened for mutations in retinal disease genes, and mutations in the following genes were found: three cases with USH2A; three cases with EYS; one case each with USH3A (CLRN1), DHX38, RHO, RPGR, and RP9." (PMID 33037922, 2021).
retinal disease (continued). "In this study, RPGRIP1, RANBP2, NPM1, PDE6D, NPHP5, and ABCA4 genes were selected on the basis of interaction with RPGR or RPGRIP1 or their implication in related retinal diseases, and were investigated as candidate genetic modifiers of XLPRA1." (PMID 17653054, 2007). "In the current cohort of RPGR carriers, there were no genotype–phenotype correlations relating to the type or location of mutation on the RPGR gene with a retinal disease phenotype." (PMID 40004550, 2025). "RPGR carriers with a male pattern phenotype displayed significant inner-retinal thinning (in comparison to the healthy controls) in the central 3–7° from the fovea, and all carriers with milder retinal disease displayed this feature at 3–5° from the fovea." (PMID 40004550, 2025). "Nevertheless, a sufficiently high number of glutamic acid residues in this region need to be preserved for glutamylation, a post-translational modification essential for RPGR function and the absence of which causes retinal disease." (PMID 34257417, 2022). "RPGR complexes with other IRD proteins at the cilium, including CEP290, which is required for ciliogenesis and normal cilia trafficking, and pathogenic variants in this gene also cause a range of syndromic retinal diseases." (PMID 35330501, 2022). "Here we show that RPGR retinal disease, studied in a single cohort of 116 male patients, leads to a clear progressive shift from rod- to cone-dominating phenotype as the RPGRORF15 variant location approaches the distal part of the Open Reading Frame 15 (ORF15) region." (PMID 36445968, 2022). "The absence of this posttranslational modification in the RPGR protein diminish the protein function and is associated with retinal diseases." (PMID 34659350, 2021). "Although mice lacking RPGR demonstrate a slower progression of retinal disease than human patients, early mislocalization of cone opsin is a hallmark feature of the disease in mice." (PMID 34257417, 2022). "However, this has not been investigated in relation to RPGR carriers of varying retinal disease severity." (PMID 40004550, 2025).
myopia (18 papers, 2010 to 2025). "A recent study found that high-dose atropine effectively reduced myopia progression in children with a strong monogenic driver, although axial elongation was notably harder to control in those with mutations in RPGR." (PMID 40535564, 2025). "The association between myopia and RPGR carriers has been well documented in the past; however, conflicting reports exist, with some studies reporting inter-eye symmetry and others asymmetry of myopia." (PMID 40004550, 2025). "While the findings regarding RPGR variants remain mixed, with some studies indicating a high myopia association, our cohort showed that RPGR patients were relatively emmetropic, supporting Yassin’s findings." (PMID 40935931, 2025). "Patients with RPGR-related XLRP commonly exhibit high myopia, and studies have interrogated the association between RPGR mutations and high myopia." (PMID 41153400, 2025). "There were no obvious differences between RPGR and RP2 carriers with respect to BCVA, visual field area, but myopia was significantly more severe in female carriers with RPGR mutation." (PMID 30917587, 2019). "XLCORD caused by pathogenic RPGR variants affects males with various onsets ranging from the second to the fourth decade, myopia, generalized cone rod dysfunction (occasionally with rod dysfunction), and diverse rates of progression." (PMID 31645972, 2019). "XLRP caused by pathogenic RPGR variants is one of the most severe forms of RP, with early onset of disease, night blindness, myopia, severe generalized rod and cone dysfunction, and progression to legal blindness by the third or fourth decade." (PMID 31645972, 2019). "Multiple studies have shown that female heterozygous RPGR mutation carriers had early-onset high myopia in one of two eyes, especially those with protein truncating variants." (PMID 30245926, 2018). "Additionally, RPGR carriers with mutations in the ORF15 site exhibited greater myopia (p = 0.044) and reduced BCVAs (p < 0.001), average retinal thresholds (p = 0.006), and HoV volumes compared to the healthy controls (p = 0.006)." (PMID 40004550, 2025). "Mutations in RPGR can lead to X-linked retinitis pigmentosa and myopia." (PMID 38662103, 2024). "This emphasizes the importance of performing a comprehensive examination of patients with early-onset high myopia and of considering the possibility that RPGR variants may exist in these patients." (PMID 34745198, 2021). "Taken together, these results suggest that the selection and prioritization of patients for clinical trials should consider the patient's age, the RP form according to the fundus appearance, the presence of high myopia, as well as the localization and type of causative variants in the RPGR gene." (PMID 33372982, 2020). "Therefore, the findings of our study do necessarily signify that moderate to high myopia is more prevalent in females in this family with an ORF15+577_578delAG mutation, and it is conceivable that high myopia is also a variable expression of this RPGR mutation." (PMID 20806050, 2010). "High myopia was associated with the NYX (n = 4, −8.34 ± 1.75D), RPGR (n = 3, −8.63 ± 2.69D) and TRPM1 (n = 3, −8.92 ± 2.63D) genes." (PMID 41465105, 2025). "Among these ocular disease related or direct high myopia related genes, five genes (CSMD1, HSPG2, RPGR, SEMA4A and USH2A) have pathogenic variants in multiple patients." (PMID 30245926, 2018). "Other studies have found high myopia in patients with XLRP, particularly in females with RPGR mutations." (PMID 20806050, 2010). "Thus, our observation that early-onset cone degeneration is associated with high myopia is also seen in CEP290; another ciliary protein which shares a similar structural and functional role with RPGR." (PMID 40535564, 2025). "Uniquely, RPGR is a ciliary protein with a dual role in photoreceptor structure (via cilia) and light signaling pathways (e.g., dopamine metabolism) which may synergistically drive myopia." (PMID 40535564, 2025).